EGFR (epidermal growth factor receptor)
Diseases named in the same sentence as EGFR in open-access papers (continued):
Sharing a sentence is not in itself a finding about the gene and the disease.
lung cancer (continued). "Epidermal growth factor receptor (EGFR) inhibitors, as cetuximab or panitumumab, have become widely prescribed anticancer drugs for the treatment of colorectal, head and neck and lung cancer, alone or in combination with traditional chemotherapy." (PMID 20398332, 2010). "We used the A549 cell line model of NSCLC, which expresses EGFR and HER-2, to test the preclinical efficacy of lapatinib against lung cancer." (PMID 20459769, 2010). "The expression of EGFR and COX-2 was detected in 89 primary lung cancer tissues, 12 premaliganant lesions, 12 lymph node metastases, and 10 normal lung tissues as the control by immunohistochemical method on a tissue microarray section." (PMID 20673501, 2010). "Cyclin D1 has also been introduced as an important biomarker among EGFR, K-RAS and VEGFR in the BATTLE trial focusing on personalized therapy for lung cancer." (PMID 21165163, 2010). "To investigate this possibility, we examined breast (SKBR3; HER2 amplified) and lung cancer (HCC827; EGFR del E746_750) cell lines either unprocessed or spiked into normal blood, then processed with the CPK or CEK methods." (PMID 20461092, 2010). "We have previously reported that mutations of EGFR, KRAS, BRAF and HER2 were mutually exclusive in 691 resected NSCLC tumors indicating that a single activating mutation in the EGFR-RAS-RAF signaling pathway may be sufficient for the pathogenesis of many lung cancers." (PMID 19238210, 2009). "The primary method to detect EGFR copy number is FISH (Fluorescence in Situ Hybridization), that in lung cancer requires a precise standardization due to the presence of intratumor heterogeneity and high frequency of chromosome 7 polysomy." (PMID 19889201, 2009). "However, unlike with lung cancer (EGFR gene amplification, EGFR gene mutation, lack of KRAS mutation) and colorectal cancers (lack of KRAS mutations), molecular markers of sensitivity to EGFR blockade are currently unknown for gastroesophageal carcinomas." (PMID 19636422, 2009). "In this study, we utilized a GEPR for erlotinib, an EGFR-TKI, which was generated in lung cancer cell lines, to test its predictive capacity in KRAS-wildtype mCRC patients treated with the anti-EGFR mAB cetuximab." (PMID 19439077, 2009). "Interestingly, KRAS mutations may also predict lack of response to EGFR tyrosine kinase inhibitors (TKI) in lung cancer, suggesting a common mechanism of resistance to anti-EGFR therapies in these two tumor types." (PMID 19439077, 2009). "As MET and EGFR often co-express in lung cancer cells, we asked if there is signalling cross-activation between MET and EGFR pathways." (PMID 19238632, 2008). "To further test the role of MET inhibition in EGFR-TKI-resistant lung cancer in vivo, we developed stable luciferase-expressing H1975 lung cancer cells using lentivirus transduction." (PMID 19238632, 2008). "Because the 181946C>T polymorphism does not result in an amino acid change, nor does it reside within the functional domain, the observed effect of the 181946C>T polymorphism on lung cancer may be due to LD with other functional EGFR variant(s) that were not tested in this study." (PMID 17956637, 2007). "Growth factor receptors like EGFR, HER-2, and c-Kit have recently emerged as promising targets for novel therapeutic agents in malignancies such as lung cancer, breast cancer, and gastrointestinal stromal tumour (GIST)." (PMID 17876336, 2007). "Gefitinib, a small molecule tyrosine kinase inhibitor of the Epidermal Growth Factor Receptor (EGFR), has shown limited efficacy in the treatment of lung cancer." (PMID 17626639, 2007). "The effect of gefitinib was investigated on the phosphorylation of EGFR, Akt, p44/42 MAP kinase, and p38 MAP kinase, in serum-starved, gefitinib-pretreated lung cancer cells." (PMID 17150102, 2006).
lung cancer (continued). "The protein expression levels and phosphorylation status of EGFR, Her2, Her3, Akt, p44/42, p38 MAP kinase, and PTEN were analyzed in all 23 lung cancer cell lines by measuring the signal intensity using NIH Image (ImageJ1.32j)." (PMID 17150102, 2006). "Over-expression of truncated epidermal growth factor receptor (EGFR) occurs in a variety of malignancies including glioblastoma multiforme, breast and lung cancer." (PMID 11355942, 2001). "The predominance of EGFR mutation and the relative absence of smoking-related mutational signatures distinguish LCINS from conventional lung cancer." (PMID 41594221, 2026). "By integrating structural bioinformatics with molecular and expression data, this study aims to reinforce the role of EGFR, ALK, KRAS, and PD-1 as precision targets in lung cancer, providing a foundation for future diagnostics, therapeutic design, and personalized oncology strategies." (PMID 40927719, 2025). "To address how EGFR expression relates to TKI sensitivity in general, we categorized 23 EGFR mutant lung cancer cell lines into EGFR-low and EGFR-high groups based on their EGFR mRNA expression and compared their IC50 values with EGFR TKIs available in the CCLE database." (PMID 39747003, 2025). "As dysregulation of cell-ECM interactions is a common feature in cancers, our study raises the possibility that EGFR and EFNB1 cooperate to regulate cell-matrix adhesion in cancer types where both proteins are overexpressed, possibly including brain, breast, and lung cancers." (PMID 40619000, 2025). "GBP1 has been shown to promote proliferation, migration, and metastasis in lung cancer by binding to indoleamine 2,3-dioxygenase 1 (IDO1) and to enhance resistance to epidermal growth factor receptor (EGFR) inhibitors by interacting with phosphoglycerate kinase 1 (PGK1)." (PMID 40975978, 2025). "In EGFR-mutant lung cancer, IL-8 is upregulated in gefitinib-resistant cells, and high plasma IL-8 levels are correlated with shorter progression-free survival (PFS) in patients treated with EGFR-TKIs." (PMID 40002883, 2025). "In Taiwan, NGS has not been fully reimbursed for patients with lung cancer, nor have novel agents targeted acquired resistance to EGFR TKI." (PMID 40470164, 2025). "In our study, we observed that ORR and DCR were not affected by EGFR mutation-positive, ALK-positive, and ROS-1-positive in patients with advanced lung cancer who received camrelizumab-based therapies." (PMID 40124372, 2025). "In case of lung cancer, various targets like HER2, EGFR, MAGE-A1, MUC1, mesothelin (MSLN), CEA, inactive Tyrosine-protein kinase transmembrane receptor ROR1, PD-L1, B7-H3 and Chemokine receptor CXC4 have been identified and clinical studies have already been performed." (PMID 40922740, 2025). "Consistent with what is observed in patients, the implantable models of either EGFR- or ALK-driven lung cancers show no response to anti-PD-1 therapy but show a clear role for adaptive immunity in the response to TKIs." (PMID 40805126, 2025). "Despite new discoveries and treatment including targeted agents, e.g., epidermal growth factor receptor inhibitors, dedicated to precision medicine, the overall survival rates of lung cancer patients have not shown significant improvement." (PMID 41480542, 2025). "Our study found that the median PFS and median OS for EGFR-positive nonsquamous lung cancer patients was 15 and 38 months, respectively, which is higher than what has been reported in the literature." (PMID 41333366, 2025). "The absence of PTEN in lung cancer cells is a pivotal determinant of their resistance to EGFR inhibitors." (PMID 40129883, 2025).
lung cancer (continued). "The selected cell lines include A549, a lung cancer cell line that is characterized by its high expression of EGFR; SKOV-3, an ovarian cancer cell line, selected for its overexpression of both EGFR and HER2; and the breast cancer cell line (SKBR-3), characterized by HER2 overexpression." (PMID 40732338, 2025). "This study aims to isolate and characterize extracellular vesicles (EVs) released by mutant EGFR lung cancer cell line PC9 and compare them with wild-type EGFR lung cancer cell line A549, while also evaluating the effect of gefitinib treatment on EV secretion and cargo composition." (PMID 40210802, 2025). "A study in China screened 391 patients with lung cancer without available tissue for EGFR alterations using LB." (PMID 41323435, 2025). "Studies were conducted on different lung cancer cell lines, including H1975 cells, in which ethanol extract of Scutellaria baicalensis and triterpenes extracted from H. diffusa effectively induced apoptosis by inactivating STAT3 in EGFR-TK-resistant cells." (PMID 40365309, 2025). "This inhibitory role of RKIP has been reported in NSCLC and other cancers but not in these lung cancer cells, which are EGFR mutants." (PMID 40720248, 2025). "Importantly, treatment with PYCR1-IN-1, a selective PYCR1 inhibitor, significantly suppressed EGFR- and TLR-induced tumor spheroid growth in multiple lung cancer cell lines, underscoring PYCR1’s potential as a therapeutic target." (PMID 41254241, 2025). "To determine the potential media-related effects, we evaluated drug responses in two commercial lung cancer cell lines: HCC827, harboring an amplification of EGFR and exon 19 deletion, and H1869, a squamous cell carcinoma cell line with unknown EGFR status." (PMID 40723246, 2025). "Background/Objectives: Immune checkpoint inhibitors (ICIs) benefit some lung cancer patients, but their efficacy is limited in advanced lung adenocarcinoma (LUAD) with EGFR mutations (EGFRm), largely due to a non-immunogenic tumour microenvironment (TME)." (PMID 40149368, 2025). "Furthermore, inhibition of Eg5 demonstrated efficacy in EGFR-TKI-resistant and cisplatin-resistant lung cancer cells, and combining Eg5 and BCL2L1 inhibitors effectively killed EGFR-mutant LUAD cells refractory to EGFR TKIs." (PMID 40002279, 2025). "Similar to the ALK‐positive subtype, the EGFR‐driven lung cancer is also common for never smokers or light smokers." (PMID 41213866, 2025). "By blocking EGFR phosphorylation, restoring PTEN, and activating caspases, it effectively suppresses tumor growth and overcomes resistance, highlighting its potential as a supportive therapy in TKI refractory lung cancer." (PMID 40728967, 2025). "In contrast, the ABCP group had a greater representation of patients with EGFR-mutant lung cancer, females, and never-smokers." (PMID 41300997, 2025). "Given the established role of PYCR1 in regulating EGFR- and TLR-mediated signaling, we investigated whether PYCR1 influences lung cancer progression in response to EGF and TLR agonists." (PMID 41254241, 2025). "The binding prevents the translational inhibition of epidermal growth factor receptor (EGFR) and insulin-like growth factor 1 receptor (IGF1R), which both are essential cellular oncogenic proteins that drive carcinogenesis in human cancers such as lung cancer." (PMID 39736850, 2025). "As evidenced by early studies of epidermal growth factor receptor (EGFR) inhibitors in lung cancer, the survival advantage from erlotinib and gefitinib was not demonstrated in clinical trials until predictive EGFR mutations were identified." (PMID 40615718, 2025).
lung cancer (continued). "In current (mostly phase I) trials in lung cancer, the CAR-T cell’s extracellular single-chain variable fragment (scFv) has been engineered to bind to TAA ligand targets such as CEA, MUC1, or EGFR in NSCLC trials, and DLL3 in SCLC, using mostly autologous cell preparations." (PMID 41479781, 2025). "Many studies have demonstrated that lung cancer patients with EGFR kinase domain mutations benefit from EGFR-TKI treatments, while those with wild-type EGFR do not show similar advantages." (PMID 40864738, 2025). "The immuno‐fluorescence experiments revealed that GM‐protac could degrade EGFR and inhibit HDAC activity, similar in H1975 lung cancer mice." (PMID 40842076, 2025). "Furthermore, this study suggests that epigenetic regulators, including the NuRD (MTA2) and ncBAF (BRD9) complexes, contribute to EGFR and GLI-1 expression and interact with MEOX2 in lung cancer cells." (PMID 39971779, 2025). "Unlike other studies that included various lung cancer subtypes, our analysis was limited to EGFR-mutant cases." (PMID 40723259, 2025). "In the context of epigenetic initiation, different histological types of lung cancer each exhibit distinct genomic characteristics, such as RB1 and MYC alterations in SCLC, NFE2L2, TP63 and NOTCH1 variations in LUSC, and EGFR, KRAS and ERBB2 variations in LUAD." (PMID 40847555, 2025). "It has been well documented that there is increased prevalence of biomarker mutations, particularly epidermal growth factor receptor (EGFR), in Asian women who have never smoked with lung cancer." (PMID 41282554, 2025). "EGFR, a member of the RTK family, is a well-established driver of lung cancer." (PMID 41019373, 2025). "Our findings indicated that panduratin A, isolated from B. rotunda, exhibits significant anti-lung cancer activity and presents a promising therapeutic option for NSCLC patients with both the wild-type and mutant EGFR, while also demonstrating low toxicity to MRC5 normal cells." (PMID 40076971, 2025). "Biomimetic SPIONs inherit native membrane proteins such as integrin αvβ3, CD47, and EGFR, enabling ligand-free homotypic recognition that has been shown to double tumor accumulation compared with non-coated SPIONs in lung cancer models." (PMID 41155938, 2025). "Furthermore, curcumin reduces EGFR protein expression in Erlotinib-resistant NSCLC (H1650) cells, hence enhancing the efficiency of Erlotinib, the recommended drug to combat lung cancer." (PMID 40490812, 2025). "In this study, western blotting and flow cytometric analyses indicated that panduratin A induces apoptosis by inhibiting phosphorylated EGFR (p-EGFR) and its downstream effectors, phosphorylated STAT3 (p-STAT3) and phosphorylated Akt (p-Akt), in both A549 and H1975 lung cancer cell lines." (PMID 40076971, 2025). "In contrast, lung cancers in nonsmokers typically have a low TMB and are often accompanied by mutations in driver genes such as EGFR resulting in limited efficacy of PD-1 inhibitors." (PMID 41035637, 2025). "Treatment with oAd-Cas12a targeting EGFR effectively knocked out approximately 25.8% of EGFR sequences in lung cancer xenografts, with no detectable off-target effects." (PMID 40968311, 2025). "In preclinical studies, gefitinib was reported to induce cell death in lung cancer cell lines harboring mutant EGFR but not wild-type EGFR." (PMID 40940888, 2025). "Treatments that have been successful in targeting single genes in other types of cancer such as EGFR in lung cancer or B-RAF in melanoma, are not effective in pancreatic cancer for this reason." (PMID 40867232, 2025). "Notably, afatinib was the first Epidermal Growth Factor Receptor (EGFR) inhibitor approved by the Food and Drug Administration (FDA) for lung cancer." (PMID 40243822, 2025). "Although specific somatic mutations—such as those in EGFR, KRAS, and EML4-ALK—have been identified, particularly in lung adenocarcinoma, they are absent in the majority of patients with lung cancer." (PMID 41241099, 2025).
lung cancer (continued). "The effectiveness of tarlatamab in neuroendocrine-transformed EGFR-mutant lung cancer has not been established." (PMID 41256964, 2025). "In contrast, lung cancers exhibit prognostic variations based on the presence of EGFR and KRAS, influenced in part due to historic availability of highly active EGFR tyrosine kinase inhibitors; in the breast, presence or absence of estrogen receptor expression dictates therapeutic options." (PMID 40647516, 2025). "Similarly, EGFR tyrosine kinase inhibitor (erlotinib) treated lung cancer cells downregulated miR21, which regulates the TNF and NF-κB signaling in mutant EGFR cells." (PMID 39948411, 2025). "While the regulation of STAT3 phosphorylation is yet to be understood, we demonstrated that it is dependent on the JAK activation but not on EGFR; the former is often overactivated in lung cancer cells." (PMID 39985075, 2025). "This case exemplifies the remarkable efficacy of precision-targeted therapy in combination with intrathecal chemotherapy, which has resulted in significant clinical improvement for an EGFR- and BRCA-mutant lung cancer patient suffering from severe and symptomatic leptomeningeal metastases." (PMID 40182045, 2025). "CUDC-101 was the first multitarget epi-drug to be trialled (ClinicalTrial.gov identifier: NCT01171924), which targets HDAC, epidermal growth factor receptor (EGFR) and human epidermal growth factor receptor 2 (HER2), in patients with advanced head and neck, breast, gastric, liver and lung cancers." (PMID 40011240, 2025). "Furthermore, western blotting and flow cytometric analyses indicated that panduratin A induces apoptosis by inhibiting p-EGFR and its downstream effectors, p-STAT3 and p-Akt, in lung cancer cells." (PMID 40076971, 2025). "A retrospective analysis was conducted on 51 patients aged over 18 years with EGFR-positive nonsquamous lung carcinoma treated at Aga Khan University Hospital between January 2017 and December 2021." (PMID 41333366, 2025). "We proceeded to co‐culture TR4‐CAR‐T cells with human lung cancer cell lines K562 (which does not express EGFR) and HCC827 (which does express EGFR)." (PMID 38853761, 2024). "Many lung cancer oncogenes were originally characterized through the analysis of lung tumors from never smokers (NSs), most notably EGFR." (PMID 38890444, 2024). "In tackling resistance to EGFR-TKI in lung cancer, Manoalide has been shown to effectively enhance the sensitivity of lung cancer cells to osimertinib by inhibiting the NRF2-SLC7A11 axis and inducing ferroptosis by down-regulation of ferritin heavy chain 1 through mitochondrial Ca2+ overload." (PMID 38515565, 2024). "However, the relationship between EGFR-TKI resistance and autophagy is still poorly understood, and TKI-modulated autophagy in lung cancer cells has been postulated to exert either cytoprotective or cytotoxic effects." (PMID 38764025, 2024). "The co-expression of EGFR and MUC1 was higher in tumor cells than EGFR combined with targets under active drug development for lung cancer such as MET, HER3 (ERBB3) or Trop2 (TACSTD2), suggesting the potential safety advantage of developing therapies targeting EGFR and MUC1." (PMID 39664199, 2024). "BMS.708163 is a gamma-secretase inhibitor and exerts antitumor effects in lung cancer by reversing EGFR inhibitor resistance, but it currently has not been reported for NPC treatment." (PMID 38532632, 2024). "EGFR inhibitors improve outcomes in EGFR-mutant lung cancers; however, 85% of never-smoker-lung AC and SCC in the USA are EGFR wild-type." (PMID 39902337, 2024). "Starting in 2010, the epidermal growth factor receptor (EGFR) kinase inhibitors erlotinib and gefitinib were introduced into routine use in Aotearoa New Zealand (NZ) for treating advanced lung cancer, but their impact in this setting is unknown." (PMID 38954434, 2024).